FER1L4 (fer-1 like family member 4 (pseudogene))
Synonyms: FER1L4P; bA563A22B.1; dJ309K20.1; C20orf124
Gene: Transcribed unitary pseudogene on chromosome 20 (35,558,866 to 35,607,494, reverse strand). Ensembl gene ENSG00000088340.
Diseases named in the same sentence as FER1L4 in open-access papers:
FER1L4 is named in the same sentence as 39 diseases in open-access papers, as found by Europe PMC text mining. Sharing a sentence is not in itself a finding about the gene and the disease. The quoted sentences say what the papers report.
gastric cancer (20 papers, 2013 to 2025). A primary or metastatic malignant neoplasm involving the stomach. "LINC01133 and the pseudogene FER1L4 are inhibitors of gastric cancer progression, with reduced expression associated with a more aggressive tumour phenotype." (PMID 38355543, 2024). "In gastric cancer tissues, FER1L4 lncRNA was associated with the tumour diameter, differentiation state, tumour classification, invasion, metastasis, TNM stage and serum CA72-4." (PMID 31443490, 2019). "Initially identified in gastric cancer, FER1L4 has since been reported to be an oncogene by modulating the PI3K/AKT pathway in various cancer cells, including osteosarcoma, hepatocellular carcinoma, and colon cancer." (PMID 41333018, 2025). "Meanwhile, FER1L4 was also found to act as a tumor suppressor in prostate cancer, gastric cancer, hepatocellular carcinoma and colon cancer cells." (PMID 36272991, 2022). "For example, lncRNA Fer-1-like family member 4 (FER1L4) has been reported to be involved in the development of gastric cancer." (PMID 33868788, 2021). "It was previously reported that FER1L4 served as a tumor suppressor in colon cancer and gastric cancer, while it showed an oncogenic role in glioma." (PMID 34289835, 2021). "The results suggested that FER1L4 has oncogenic characteristics that agree with previous studies in gastric cancer and endometrial cancer." (PMID 33868788, 2021). "In colon and gastric carcinoma, Fer1L4 exerted a tumor suppressive effect as ceRNA which regulates the expression of PTEN via the release of miR-106-5p." (PMID 31965534, 2020). "For example, LncRNA FER1L4 functions as a ceRNA to modulate PTEN expression through regulation of miR-106a-5p in gastric cancer." (PMID 30992025, 2019). "Recently, a profiling study reported that FER1L4 was a long non-coding RNA (lncRNA) strongly downregulated in gastric cancer tissue, in plasma from gastric cancer patients and in human gastric cancer cell lines." (PMID 31443490, 2019). "Long non‐coding RNAs have recently become a key regulatory factor for cancers, whereas FER1L4, a newly discovered long non‐coding RNA, has been mostly studied in gastric carcinoma and colon cancer cases." (PMID 30887657, 2019). "In this study, we further found that FER1L4 levels in the human gastric cancer cell lines AGS, MGC-803 and SGC-7901 were lower than those in the human normal gastric epithelial cell line GES-1." (PMID 26306906, 2015). "We observed that FER1L4 was downregulated in gastric cancer and that its level corresponded with that of PTEN mRNA." (PMID 26306906, 2015). "We found that FER1L4 acted as a ceRNA to regulate PTEN expression by acting as a sponge for miR-106a-5p in gastric cancer." (PMID 26306906, 2015). "The most down-regulated lncRNAs in gastric cancer tissues were FER1L4, uc001lsz, BG491697, AF131784, uc009ycs, BG981369, AF147447, HMlincRNA1600, and AK054588." (PMID 24063685, 2013). "The most down-regulated lncRNAs in gastric cancer tissues were FER1L4, uc001lsz, BG491697, AF131784, uc009ycs, BG981369, AF147447, HMlincRNA1600, and AK054588; while the most up-regulated ones were H19, HMlincRNA717, BM709340, BQ213083, AK054978, and DB077273." (PMID 24063685, 2013). "One study showed that downregulation of FER1L4 inhibited the mRNA levels of RB1 in gastric cancer." (PMID 35928868, 2022). "In conclusion, we found that FER1L4 was minimally expressed in gastric cancer." (PMID 26306906, 2015). "For example, the FER1L4/miRNA106a-5p/PTEN pathway constitutes a novel regulatory pathway that is involved in the occurrence and progression of gastric cancer." (PMID 29636075, 2018). "In our previous study, we designed a siRNA against FER1L4 and effectively reduced FER1L4 levels in the normal human gastric epithelial cell line GES-1 and the human gastric cancer cell lines AGS, MGC-803 and SGC-790124." (PMID 26306906, 2015).
gastric cancer (continued). "We measured FER1L4 and PTEN expression in 20 gastric cancer tissue samples by quantitative reverse transcription-polymerase chain reaction (qRT-PCR)." (PMID 26306906, 2015). "Moreover, FER1L4 reduced cell growth via binding with miR-106a-5p and increased the expression of PTEN at both mRNA and protein levels in gastric cancer." (PMID 35928868, 2022). "Similarly, FER1L4 reduced growth, invasion, migration and metastasis by suppressing the Hippo-YAP signaling pathway in gastric cancer." (PMID 35928868, 2022). "Here, we report that the lncRNA FER1L4 (fer-1-like family member 4, pseudogene) acts as a competing endogenous RNA (ceRNA) to regulate the expression of PTEN (a well-known tumor suppressor gene) by taking up miR-106a-5p in gastric cancer." (PMID 26306906, 2015).
glioma (12 papers, 2019 to 2024). A benign or malignant brain and spinal cord tumor that arises from glial cells (astrocytes, oligodendrocytes, ependymal cells). "The exception is a report about the Fer1L4 possible role in glioma progression, where high expression of Fer1L4 was associated with a poor disease prognosis." (PMID 32106631, 2020). "In glioma, however, FER1L4 promoted cancer progression via sponging miR-371 and upregulation of E2F1." (PMID 32140077, 2020). "The previous experimental study of this subject has preliminarily confirmed that FER1L4 is significantly higher in glioma cells than in astrocytes cell lines." (PMID 30887657, 2019). "In this study, it was found that the expression of LncRNA FER1L4 was significantly up‐regulated in high‐grade glioma patients compared with low‐grade expression." (PMID 30887657, 2019). "The knockdown of FER1L4 expression significantly inhibited the proliferation of glioma cells, proving that FER1L4 plays an oncogene role in glioma cells." (PMID 30887657, 2019). "Mining the TCGA database, a high Fer1L4 expression was reported as a predictor of a poor prognosis in glioma and as an oncogenic driver in several human cancers." (PMID 31443490, 2019). "It is further demonstrated by experiments that the FER1L4 knockdown suppresses growth of in vivo glioma." (PMID 30887657, 2019). "The results showed that the expression of FER1L4 in three cell lines of gliomas was significantly higher than that of normal astrocyte 1800 (P < 0.05) and that of FER1L4 was more highly expressed in U251 and U373MG cells." (PMID 30887657, 2019). "In support of this, our findings also suggest that higher expression of FER1L4 predicts unfavorable prognosis in glioma patients." (PMID 31681595, 2019). "Subsequently, by down‐regulating FER1L4, we confirmed that E2F1 expression was also down‐regulated and that FER1L4 and E2F1 were involved in the cell cycle of gliomas (FER1L4 regulates the cell progression in G2‐M by regulating E2F1)." (PMID 30887657, 2019). "In order to further investigate the role of FER1L4 in glioma cells, RT‐PCR was used to determine the expression of FER1L4 in glioma cells U87, U251, U373MG and normal astrocyte 1800." (PMID 30887657, 2019). "In this study, it was found that the expression of LncRNA FER1L4 is upregulated in high‐grade gliomas than in low‐grade cases and that a high expression of LncRNA FER1L4 predicts poor prognosis of gliomas." (PMID 30887657, 2019). "Further over‐expression of miR‐372 showed that the expression of FER1L4 and E2F1 was down‐regulated and the results further confirmed that as a ceRNA, FER1L4/miR‐372/E2F1 regulates the molecular mechanism of glioma cell proliferation." (PMID 30887657, 2019). "EEF1A1P9 was a protective factor (HR < 1), and ANXA2P2, FER1L4, HILS1, and RAET1K were defined as risk factors (HR > 1) in glioma." (PMID 31681595, 2019). "In our study, we screened out five pseudogenes (ANXA2P2, EEF1A1P9, FER1L4, HILS1, and RAET1K) that were differentially expressed between LGG and GBM and were associated with the prognosis of glioma patients." (PMID 31681595, 2019). "In order to further explore the effect of FER1L4 expression on the proliferation of gliomas in vivo, glioma U373MG cells were transfected by stabilizing FER1L4 siRNA." (PMID 30887657, 2019). "There was a significant positive correlation between its expression in gliomas and FER1L4 expression suggesting a synergistic effect between FER1L4 and E2F1, which participate in the malignant biological process of glioma." (PMID 30887657, 2019). "The functions and molecular mechanism of FER1L4 have been rarely reported in glioma malignant phenotypes." (PMID 30887657, 2019). "The results suggested a significant correlation between the expression of FER1L4 and E2F1 and the prognosis of glioma patients and the high expression of FER1L4 (P < 0.05) or E2F1 (P < 0.01) predicts a worse prognosis of gliomas." (PMID 30887657, 2019).
glioma (continued). "The results further proved that as a ceRNA, FER1L4/hsa‐miR‐372/E2F1 regulates the molecular mechanism of glioma cell proliferation." (PMID 30887657, 2019). "However, a recent study shows that FER1L4 is upregulated in glioma and promotes glioma proliferation and tumorigenicity." (PMID 31681595, 2019). "The results may improve our knowledge of the regulatory mechanism of LncRNA FER1L4 and provide useful indicators and methods for the clinical diagnosis and treatment of gliomas." (PMID 30887657, 2019). "WB experiment verified that FER1L4 was down‐regulated by 64% in the stably transfected cells compared with the control cells (1 × 106 per mouse) which were subcutaneously injected into the tibia of nude mice to evaluate the effect of FER1L4 on glioma production in vivo." (PMID 30887657, 2019). "The knockdown of FER1L4 expression could significantly inhibit glioma cell proliferation and cell cycle." (PMID 30887657, 2019). "In summary, there is evidence to speculate that Long Non‐Coding RNA FER1L4 may play an important role in the cycle and proliferation of gliomas cells and it may serve as a new indicator for prognosis prediction and malignancy judgement of gliomas." (PMID 30887657, 2019). "The study above showed that the expression of FER1L4 and E2F1 in different grades of glioma tissues showed a significant positive correlation." (PMID 30887657, 2019). "In addition, pseudogenes ANXA2P2, EEF1A1P9, FER1L4, HILS1, and RAET1K were found to be significantly correlated with glioma survival." (PMID 33378744, 2020). "SiRNA‐FER1L4 was transfected into glioma U251 and U373MG cells and the results indicated that it could significantly knock down the expression of FER1L4 (P < 0.01)." (PMID 30887657, 2019). "In addition, it is also found that FER1L4 can be used as competitive endogenous RNA (ceRNA) to adsorb E2F1 and thereby up‐regulate E2F1, thus promoting the cycle and proliferation of glioma cells." (PMID 30887657, 2019). "In addition, it is also found that FER1L4 can be used as competitive endogenous RNA to interact or bind with miR‐371 and thereby up‐regulate E2F1, thus promoting the cycle and proliferation of glioma cells." (PMID 30887657, 2019). "The expression of LncRNAs FER1L4 and E2F1 in gliomas at 47 different grades was detected using RT‐PCR and the results showed that the expression of FER1L4 in different grade WHO IV glioma tissues (27.32 ± 1.90) was dramatically higher than that in grade WHO III gliomas (14.24 ± 1.41) (P < 0.001)." (PMID 30887657, 2019).
endometrial cancer (11 papers, 2019 to 2024). Primary or metastatic malignant neoplasm involving the endometrium (mucous membrane that lines the endometrial cavity). "In endometrial cancer, FER1L4 acted as an independent prognostic indicator with the FER1L4 high expression group displayed markedly higher OS compared to the low FER1L4 expression group." (PMID 33962392, 2021). "lncRNA FER1L4 also has been noticed as a favorable survival marker for endometrial carcinoma, colon cancer, and osteosarcoma." (PMID 34422643, 2021). "LncRNA FER1L4 inhibited the proliferation and invasion of endometrial cancer cells by regulating PTEN." (PMID 32760226, 2020). "Other studies have shown that the expression of MEG3 and FER1L4 were decreased in EC, and high expression of MEG3 and FER1L4 inhibited the proliferation, migration and invasion of endometrial cancer cells." (PMID 32587476, 2020). "Furthermore, FER1L4 overexpression was correlated with favorable survival outcome in endometrial carcinoma patients." (PMID 35928868, 2022). "Besides, FER1L4 can be used as a prognostic biomarker, and its low expression was identified as an important independent predictor of poor survival in endometrial cancer." (PMID 33868788, 2021). "FER1L4 is an independent indicator of poor prognosis in endometrial carcinoma." (PMID 33949761, 2021). "LncRNAs that play a role in tumor suppression in endometrial cancer include: FER1L4, GAS5, MEG3, RP11-395G23.3, LA16C −313D11.11, Xist, Linc ROR, MALAT1, HOTAIR, OVAL, SRA, etc., However, the mechanism of cuproptosis-associated LncRNAs in endometrial cancer is still unclear." (PMID 37124623, 2023). "Many studies showed that FER1L4 inactivated AKT signaling to suppress cancer progression including osteosarcoma, lung cancer, hepatocellular carcinoma and endometrial carcinoma." (PMID 32140077, 2020).
colon cancer (10 papers, 2018 to 2025). "Fer-1-like protein 4 (FER1L4) levels are reduced in colon tumor specimens and is negatively associated with tumor invasion, metastasis and tumor stage, and colon cancer patients with lower FER1L4 expression have worse overall survival and disease-free survival rates." (PMID 33246471, 2020). "FER1L4 is a newly discovered lncRNA and is dysfunctional in cancers such as liver cancer, colon cancer and endometrial cancer." (PMID 34158566, 2021). "FER1L4 expression is decreased in colon cancer tissues and its overexpression impairs cell migration and invasion via downregulation of miR-106a-5p in colon cancer cells." (PMID 33246471, 2020). "FER1L4 overexpression inhibits the proliferation of colon cancer cells by acting as a ceRNA by sponging miR-106a-5p." (PMID 33246471, 2020). "Subsequent study has shown that FER1L4 can be used as an important endogenously‐competent RNA and plays a role of tumour suppressor gene in colon cancer." (PMID 30887657, 2019). "Microarray and real time PCR results showed that lncRNA fer-1-like family member 4 (FER1L4) was downregulated in gastric cancer, endometrial carcinoma and colon cancer tissues or cell lines." (PMID 30217221, 2018). "FER1L4 expression could inhibit colon cancer development and progression and could be a prognostic survival indicator in such patients." (PMID 33962392, 2021). "In colon cancer cell lines, FER1L4 expression is inversely correlated with miR-106a-5p expression." (PMID 30217221, 2018).
hepatocellular carcinoma (8 papers, 2019 to 2025). A malignant tumor that arises from hepatocytes. "For example, a previous study suggested that FER1L4 suppressed the proliferation of hepatocellular carcinoma cells through PTEN." (PMID 33868788, 2021). "FER1L4 expression is downregulated in hepatocellular carcinoma and attenuates cell proliferation, migration, and invasion by blocking the PI3K/AKT pathway." (PMID 31900200, 2020). "Studies in osteosarcoma, lung cancer, and hepatocellular cancer indicated that Fer1L4 suppresses proliferation and induces apoptosis in vivo and in vitro by inhibiting the Pi3K/AKT pathway." (PMID 31965534, 2020). "FER1L4 has been studied in several kinds of cancer, including colon cancer, gastric carcinoma, hepatocellular carcinoma, osteosarcoma, and gliomas." (PMID 31900200, 2020).
osteosarcoma (8 papers, 2020 to 2025). A usually aggressive malignant bone-forming mesenchymal neoplasm, predominantly affecting adolescents and young adults. "The evidence is that lncRNA FER1L4 has a lower expression in tissues of osteosarcoma patients, which is linked to stage and metastasis (Chen ZX." (PMID 35252166, 2022). "On the contrary, FER1L4 expression is inhibited in osteosarcoma, and overexpression of FER1L4 can alleviate osteosarcoma cell apoptosis and epithelial-mesenchymal transition by inhibiting the PI3K/AKT pathway." (PMID 39039611, 2024). "In various tumor entities such as gastric cancer, ovarian cancer, endometrial carcinoma, lung cancer, and osteosarcoma, expression of Fer1L4 was found to be decreased, whereas upregulation was reported in human glioblastoma and breast cancer." (PMID 31965534, 2020). "LncRNA FER1L4 plays an anti-tumor role in osteosarcoma development." (PMID 35252166, 2022). "In addition, FER1L4 retarded osteosarcoma tumorigenesis via sponging miR-18a-5p and increasing PTEN expression." (PMID 35252166, 2022). "In mechanism, FER1L4 suppressed tumor progression via targeting PI3K/Akt pathway in osteosarcoma." (PMID 35252166, 2022). "Fer-1-like protein 4 (FER1L4) prevented EMT initiation, controlling osteosarcoma cell proliferation via miR-18a-5p/SOCS5/PI3K/AKT signaling pathway." (PMID 38948025, 2024).
ovarian carcinoma (5 papers, 2019 to 2024). A malignant neoplasm originating from the surface ovarian epithelium. "Elevated FER1L4 can promote the sensitivity of ovarian cancer cells to paclitaxel treatment." (PMID 39039611, 2024). "LncRNA FER1L4 reduces PTX resistance of ovarian cancer cells by targeting MAPK signaling." (PMID 35132320, 2022).
breast carcinoma (4 papers, 2019 to 2024). "Positive regulation of the FER1L4 pseudogene is well known as an oncogenic driver associated with poor prognosis in other neoplasms, such as breast carcinoma and clear cell renal carcinoma." (PMID 36077612, 2022). "In breast cancer, upregulation of Fer1L4 is linked to promoter hypomethylation suggesting that Fer1L4 expression is epigenetically regulated." (PMID 31965534, 2020). "In cancer tissues such as breast cancer, enriched H3K4me3 and H3K27ac at the FER1L4 promoter were observed, while H3K27me3 was less prevalent at the FER1L4 promoter." (PMID 39039611, 2024).